ACHE (acetylcholinesterase (Yt blood group))
Diseases named in the same sentence as ACHE in open-access papers (continued):
Sharing a sentence is not in itself a finding about the gene and the disease.
COVID-19 (5 papers, 2021 to 2023). A disease caused by infection with severe acute respiratory syndrome coronavirus 2. "Therefore, analyzing CLEC12A and ACHE gene expression from blood may provide a promising approach for early risk stratification of severely ill COVID-19 patients." (PMID 36928077, 2023). "In contrast, AChE mRNA was detected in 30 (81%) COVID-19 patients and in all (100%) controls (p = 0.07)." (PMID 34088975, 2021). "In addition to CLEC12A, we also identified the time-independent increased expression of ACHE in COVID-19 patients with a worse outcome." (PMID 36928077, 2023). "The significantly lower expression of CLEC12A and ACHE in healthy controls compared to the two COVID-19 patient groups suggests that the expression of these genes might be induced during severe COVID-19 and is probably not a predisposing factor." (PMID 36928077, 2023). "The observed increased expression of ACHE would lead to a decrease in ACh levels as it is metabolized, and thus ACHE might have a proinflammatory effect in COVID-19 patients leading to a worse outcome." (PMID 36928077, 2023). "The identified biomarkers CLEC12A and ACHE might both examine the ability of an individual to inhibit upstream activation of the NF-κB pathway, albeit by different mechanisms, and thus the ability to prevent an overwhelming immune response in COVID-19." (PMID 36928077, 2023). "In principle, the increased expression of ACHE in COVID-19 non-survivors and the increased expression of CLEC12A in COVID-19 survivors could be due to either COVID-19 itself or might represent an unknown predisposing factor for the development of severe COVID-19." (PMID 36928077, 2023).
glioblastoma (5 papers, 2008 to 2025). The most malignant astrocytic tumor (WHO grade IV). "In an in-vitro model containing SH-SY5Y neuroblastoma cells, U343 glioblastoma cells, and human peripheral blood mononuclear cells, we found that midazolam altered the activity of acetylcholinesterase /buturylcholinesterase (AChE / BChE)." (PMID 35802656, 2022). "Overexpression of two short (AChE-S, AChE-R) and two N-terminally extended AChE variants(N-AChE-S, N-AChE-R), was induced by transient transfection of mouse primary cortical cells, HEK 293 embryonic kidney cells, U87MG glioblastoma, T84 lung epithel and CHO hamster ovary cells." (PMID 18769671, 2008). "This study identified six PMRGs (SARDH, ACHE, ADSL, PNPLA3, MAPK1 and SREBF2) as potential prognostic biomarkers for glioblastoma." (PMID 40313243, 2025).
glioma (5 papers, 2021 to 2025). A benign or malignant brain and spinal cord tumor that arises from glial cells (astrocytes, oligodendrocytes, ependymal cells). "We predicted interactions between topotecan, irinotecan, and cryptotanshinone and acetylcholinesterase (AChE), a newly recognized marker for glioma." (PMID 40475540, 2025).
Hirschsprung disease (5 papers, 2016 to 2024). Hirschsprung disease (HSCR) is a congenital intestinal motility disorder that is characterized by signs of intestinal obstruction due to the presence of an aganglionic segment of variable extent in the terminal part of the colon. "The erythrocyte AChE is used as diagnostic marker in Hirschsprung’s disease." (PMID 28885588, 2017). "Finding rare AChE-positive neurites protruding into the LP is described to be a relatively common finding in suction biopsies from pediatric patients who do not suffer from Hirschsprung disease." (PMID 32838761, 2020).
psychosis (5 papers, 2016 to 2024). "Ketamine has already been established to reduce the concentration of acetylcholine in hippocampal region of brain by the blockade of nAChR with increase of AChE activity related to cause cognitive symptoms of psychosis." (PMID 28942680, 2017). "Gallic acid, one of the physiological compounds of Codium fragile, reduced the activity of AChE in ketamine-induced psychosis mice." (PMID 37629080, 2023). "By inhibiting AChE, donepezil improves the cognitive and behavioural signs and symptoms of AD, which may include apathy, aggression, confusion, and psychosis." (PMID 38791206, 2024). "The limited data from a discontinued trial investigating whether treatment with an AchE inhibitor in PD patients with mild visual hallucinations delays progression to psychosis suggest a watchful waiting approach rather than early treatment with rivastigmine." (PMID 39046524, 2024).
status epilepticus (5 papers, 2015 to 2023). Status epilepticus is defined as a continuous seizure lasting more than 30 min, or two or more seizures without full recovery of consciousness between any of them. "Further, the BLA is known to contribute directly to status epilepticus as produced by exposure to the OP-based AChE inhibitor soman, through a mechanism that involves inhibition of AChE." (PMID 36479275, 2022). "AChE hydrolyzes acetylcholine into acetic acid and choline at the synaptic cleft, and a decrease in AChE activity results in the accumulation of acetylcholine, inducing neuronal hyperexcitability and the development of status epilepticus." (PMID 35336729, 2022).
Cerebral ischemia (4 papers, 2011 to 2021). Restriction of arterial blood supply to the brain associated with insufficient oxygenation to support the metabolic requirements of the tissue. "Our study demonstrates that XIAP overexpressed BMSCs can inhibit the apoptosis of brain nerve cells and the activation of astrocytes, increase AchE activity, and inhibit Ach content, so as to lower the CP caused by cerebral ischemia and hypoxia in rats." (PMID 31660045, 2019). "Collectively, the results of this study highlights that BMSCs modified by XIAP can inhibit the apoptosis of brain nerve cells and the activation of astrocytes and increase the activity of AchE, so as to lower the CP caused by cerebral ischemia and hypoxia in rats." (PMID 31660045, 2019). "Our study demonstrates that AChE level is elevated in the early course of brain ischemia as a trigger for the inflammatory response, and TSPO level is elevated persistently throughout the post-ischemic injury in the brain." (PMID 34072449, 2021). "In patients with cerebral ischemia, the lesions are located in the hippocampus and cortex where the activity of ChAT increases, while the activity of AChE decreases." (PMID 27293454, 2016). "The present results demonstrated that focal cerebral ischemia induced by middle cerebral artery occlusion (MCAO) produced severe deficits in performance on the Morris water maze along with signs of neurodegeneration, including decreased ChAT and AChE activity in the hippocampus." (PMID 19395577, 2011).
chronic kidney disease (4 papers, 2019 to 2025). Impairment of the renal function secondary to chronic kidney damage persisting for three or more months. "Though many studies showed decrease in AChE expression in chronic kidney disease, the present study showed that Unix was accompanied by a significant increase in both mRNA expression and activity assay of AChE in hippocampal homogenates." (PMID 36469209, 2023).
Hypercholesterolemia (4 papers, 2017 to 2023). An increased concentration of cholesterol in the blood. "In this context, it is worth mentioning that the enhanced AChE activity in the hippocampus and prefrontal cortex was previously proposed as an early event linked to hypercholesterolemia- or high-fat diet-induced alterations in cognitive function." (PMID 36394711, 2023). "The present study provided significant evidence of hypercholesterolemia-induced global loss of AChE activity with mitochondrial dysfunction and inflammation in discrete brain regions." (PMID 29263397, 2017). "This can lead to a meal containing phlorotannins and small peptides with the capacity to inhibit AChE and reduce diet cholesterol intestinal permeation as well as hypercholesterolemia through the inhibition of HMGR." (PMID 32708417, 2020). "Indeed, there is evidence of increased AChE activity in patients with familial hypercholesterolemia and in animal models of hypercholesterolemia." (PMID 31417354, 2019). "Here, we aimed to investigate the impact of hypercholesterolemia on the functional status of AChE and mitochondrial complexes, and inflammation in four discrete brain regions (cortex, striatum, hippocampus and substantia nigra), to unveil its influences on brain functions." (PMID 29263397, 2017).
insomnia (4 papers, 2022 to 2026). A sleep disorder characterized by difficulty in falling asleep and/or remaining asleep. "Increased serum acetylcholinesterase (ACHE), and accordingly decreased acetylcholine, can hence accentuate the release of pro-inflamed cytokines by macrophages related to insomnia." (PMID 39410900, 2025).
osteoporosis (4 papers, 2020 to 2024). A condition of reduced bone mass, with decreased cortical thickness and a decrease in the number and size of the trabeculae of cancellous bone (but normal chemical composition), resulting in increased fracture incidence. "In line with it, AChE is highly expressed on bone cells, especially during osteoblastogenesis, suggesting that AChE can be a therapeutic target for treating osteoporosis." (PMID 33076329, 2020). "To conclude, current and emerging therapeutics for osteoporosis targeting AChE will be highlighted." (PMID 33585459, 2020). "We conclude that AChE may be a potential therapeutic target for bone diseases like osteoporosis." (PMID 33585459, 2020). "Among them, ACHE and FN1 are already targeted by approved drugs, hinting at their potential therapeutic role in treating osteoporosis." (PMID 39526243, 2024). "Importantly, the druggable evaluation revealed that ACHE and FN1 were targets of currently approved drugs, highlighting the importance of existing medications that could potentially be repurposed or serve as the basis for the development of new treatments for osteoporosis." (PMID 39526243, 2024).
viral infection (4 papers, 2009 to 2017). "It is reasonable to assume that there are other EVs, CD45-negative and AChE-negative, that carry gp120 and may affect viral infection." (PMID 28490736, 2017). "While a link between AChE activity and HIV-1 viral load has not been made, infection with herpes simplex virus type 1 (HSV-1) results in a steady decline in the enzymatic activity of AChE12, indicating that AChE or BChE may play a role in viral infection." (PMID 28338013, 2017).
anemia (3 papers, 2019 to 2024). A reduction in the number of red blood cells, the amount of hemoglobin, and/or the volume of packed red blood cells. "Additionally, scopolamine (i.e., a nonselective anticholinergic medication) was found to increase AChE activity in several different experimental models, though the role of anticholinergic-induced AChE overexpression in the pathophysiology of anemia is still to be elucidated." (PMID 34682773, 2021).
cyst (3 papers, 2017 to 2021). A sac-like closed membranous structure that may be empty or contain fluid or amorphous material. "The AChE activity of T. crassiceps whole cyst homogenate was less sensitive to eserine inhibition, only displaying strong inhibition at a much higher eserine concentration (100 μM)." (PMID 33347447, 2020). "Further, a different pattern of AChE distribution within the cyst is observed between the two species–T." (PMID 33347447, 2020). "AChE activity in T. crassiceps cyst membrane, cyst vesicular fluid and excretory/secretory extracts was highly sensitive to eserine inhibition, with strong inhibition apparent at low (1 μM) eserine concentration." (PMID 33347447, 2020). "Whole larvae stained for AChE revealed that staining localised to numerous small protrusions on the surface of the cyst tegument membrane (bottom-right panel)." (PMID 33347447, 2020).
Encephalopathy (3 papers, 2021 to 2023). Encephalopathy is a term that means brain disease, damage, or malfunction. "They described that the longitudinal measurement of AChE activity over several consecutive days revealed a change from baseline only in septic patients with suspected sepsis-associated encephalopathy (SAE)." (PMID 37629287, 2023).
endothelial dysfunction (3 papers, 2008 to 2025). In vascular diseases, endothelial dysfunction is a systemic pathological state of the endothelium (the inner lining of blood vessels) and can be broadly defined as an imbalance between vasodilating and vasoconstricting substances produced by (or acting on) the endothelium. "AChE and DGKZ directly modulate smooth muscle function, while NLRP3 inflammasome contributes to endothelial dysfunction and smooth muscle cell pyroptosis, and PLD2 is involved in angiotensin generation." (PMID 39981435, 2025).
eosinophilia (3 papers, 2022 to 2023). "When Alternaria was co-administered with enzymatically active AChE, elevated numbers of neutrophils were observed in the lungs, but eosinophilia was strikingly reduced in both sites." (PMID 35711456, 2022). "BALB/c mice intranasally challenged with AA extract and active secretory AChE derived from Nb had increased CXCL1/CXCL2 levels but reduced eosinophilia, M2 macrophages, and IL-5 and IL-13 levels in the lung tissue compared to both the PBS- and inactive AChE-treated controls." (PMID 36704754, 2022).
functional dyspepsia (3 papers, 2017 to 2023). "Acotiamide, a new selective inhibitor of acetylcholinesterase (AChE) that impedes the degradation of ACh expelled from the parasympathetic nerve endings and elevates ACh levels in the synaptic gap, has been administered to manage functional dyspepsia." (PMID 37958499, 2023). "Indeed, one of the ACHE inhibitors, acotiamide is approved as a prokinetic agent for treating functional dyspepsia." (PMID 28284192, 2017).
HIV-1 infection (3 papers, 2017 to 2022). The type species of lentivirus and the etiologic agent of acquired immunodeficiency syndrome (AIDS). "AChE activity and Tsg-101 expression, another EVs marker, increased with the pelleted EVs after HIV-1 infection, as expected." (PMID 33925397, 2021). "Future studies are needed to investigate the role of SE-bound AChE, as well as other SE-bound proteins/enzymes in modifying processes that inhibit HIV-1 infection, and SE isolated from semen stored for at least 30 years will be valuable for such studies." (PMID 28338013, 2017). "However, 30 years of prolonged freezing of seminal fluid at −80 °C before isolation of EVs decreased the capability of EVs to inhibit HIV-1 infection in cells via a decline of acetylcholine-esterase (AChE) activity." (PMID 35629364, 2022). "Indeed, the correlation between decreased AChE activity and loss of HIV-1 inhibition by SE following prolonged freezing suggest that prolonged freezing of semen may concurrently or independently alter the activities of proteins that inhibit HIV-1 infection." (PMID 28338013, 2017). "These correlative analyses suggest that the AChE activity of SE or other enzymes such as butyrylcholinesterase (BChE) that is capable of hydrolyzing acetylcholine may play a role in the SE-virus inhibitory interaction in the pre-incubation model of HIV-1 infection." (PMID 28338013, 2017).
hyperlipidemia (3 papers, 2015 to 2025). "Simvastatin reversed hyperlipidemia and significantly rectified the deleterious effect of AlCl3 on AChE activity." (PMID 25802481, 2015). "Given the potential interaction between GPA and ACHE, we hypothesize that GPA may not only improve hyperlipidemia but also restore ACHE activity reduced by high cholesterol, thereby enhancing cognitive function." (PMID 40989883, 2025).
inflammatory bowel disease (3 papers, 2017 to 2022). A spectrum of small and large bowel inflammatory diseases of unknown etiology. "Further, human patients with inflammatory bowel disease exhibit increased levels of miR-132-3p in intestinal tissue biopsies, with corresponding decreases in circulatory AChE activity, relative to healthy controls, suggesting miR-132 involvement in IBD alongside with its stress-related target AChE." (PMID 28667373, 2018).
Lewy bodies dementia (3 papers, 2022 to 2024). "BChE expression is increased in the brains of AD and Lewy bodies dementia patients, when AChE expression is markedly decreased." (PMID 38887858, 2024).
liver cirrhosis (3 papers, 2012 to 2021). "In summary, while enzyme levels remain unchanged, expression levels of the different AChE variants are substantially altered in liver cirrhosis." (PMID 23028565, 2012). "It is also important to further define the nature of the AChE species which is increased in liver cirrhosis." (PMID 23028565, 2012). "Analysis of the levels of liver AChE transcripts indicated that all AChE molecular isoforms appear to be similarly altered in liver cirrhosis." (PMID 23028565, 2012). "Using the rat as an animal model with low serum BChE activity, we have reported that AChE is significantly altered during liver cirrhosis." (PMID 23028565, 2012).
liver disorder (3 papers, 2012 to 2024). A disease involving the liver. "In conclusion, this is the first study to reliably demonstrate that liver disease affects the expression and levels of AChE in human liver and serum." (PMID 23028565, 2012).
megacolon (3 papers, 2017 to 2025). "This collective increase in megacolon incidence was associated with more extensive aganglionosis as assessed via staining of AChE activity in the myenteric plexus." (PMID 32898154, 2020). "The colon segment that was surgically resected for the correction of the megacolon did not have ganglion cells present in the three patients who were diagnosed as normal using HE staining, which coincides with the diagnosis observed on the AChE assay." (PMID 29212517, 2017).
myocardial infarction (3 papers, 2019 to 2023). Gross necrosis of the myocardium, as a result of interruption of the blood supply to the area, as in coronary thrombosis. "Several studies reported that inhibition of AChE exerted beneficial effects on autonomic function in various heart diseases including myocardial infarction and DIC." (PMID 37691124, 2023).
Paralysis (3 papers, 2016 to 2022). Paralysis of voluntary muscles means loss of contraction due to interruption of one or more motor pathways from the brain to the muscle fibers. "AchE inhibition results in a buildup of acetylcholine, causing flexion of muscles, evident as paralysis." (PMID 35373186, 2022). "Taken together, these findings suggest that CLE metabolites alternatively decrease AB1–42 aggregation and paralysis prevalence independently of free radical scavenging and AChE inhibition, and this warrants further investigation on the bioactive compounds of CLE." (PMID 28536360, 2017).
poisoning (3 papers, 2013 to 2017). A condition or physical state produced by the ingestion, injection, inhalation of or exposure to a deleterious agent. "The principal toxicity of acute organophosphate (OP) pesticide poisoning is the disruption of neurotransmission through inhibition of acetylcholinesterase (AChE)." (PMID 23631360, 2013). "AChE levels were not available for most patients and therefore proposed comparison in organophosphate poisonings was not performed." (PMID 23990989, 2013).